DPP4 (dipeptidyl peptidase 4)
Diseases named in the same sentence as DPP4 in open-access papers (continued):
Sharing a sentence is not in itself a finding about the gene and the disease.
colorectal cancer (continued). "Very recent studies have reported exosomes enriched in CD26/DPP4 in a colorectal cancer context and related to angiogenesis." (PMID 36230486, 2022). "The inhibition of DPP4 led to the suppression of breast cancer tumor growth and displayed a positive trend in OS of colorectal cancer and prostate cancer." (PMID 33796097, 2021). "The expression of DPP4 in colorectal cancer, malignant mesothelioma, and hematological malignancies is high and is related to tumor progression." (PMID 34955820, 2021). "In colorectal cancer, the activity of DPP4 is blocked by transcription-independent method, so as to inhibit Ferroptosis." (PMID 34839280, 2021). "CD26 protein (sCD26) and its dipeptidyl peptidase IV (DPP4) enzymatic activity in circulation have been proposed as biomarkers for colorectal cancer and other diseases." (PMID 32051696, 2020). "The aim of this study was to analyse if anti-CD26 autoantibodies are related to sCD26 and DPP4 and to determine their relevance in a context of colorectal cancer screening for complementing the value of sCD26 and DPP4 as biomarkers." (PMID 32051696, 2020). "Many studies have demonstrated that serum DPP4 is significantly lower in different tumors, including head and neck squamous cell carcinoma, colorectal cancer, stomach, and gynecological tumors." (PMID 27936466, 2017).
colorectal cancer (continued). "Soluble CD26 (sCD26), a glycoprotein with dipeptidyl peptidase (DPP4) enzymatic activity, can contribute to early diagnosis of colorectal cancer and advanced adenomas and has been studied, including for prognostic purposes, across various other types of cancer and disease." (PMID 39001488, 2024). "Plasma dipeptidyl peptidase-4 (DPP4) levels were significantly lower in patients with colorectal and liver cancers, and animal studies also showed DPP4 inhibitors (DPP4is) have procarcinogenic effects in colorectal cancer." (PMID 35600378, 2022). "Indeed, the DPP4 inhibitor vildagliptin has been demonstrated to suppress lung metastasis of colorectal cancer via reduced autophagy, increased apoptosis, and inhibition of the cell cycle regulator phospho-CDC2 (pCDC2) in a syngeneic mouse model." (PMID 35053615, 2022). "Based on those findings, we investigated whether DPP4-inhibitors may be used in the management of colorectal cancer." (PMID 34298800, 2021). "DPP4 (dipeptidyl peptidase 4) is considered as a ferroptosis driver in colorectal cancer." (PMID 34307361, 2021). "Although there are some concerns regarding DPP-4 inhibitors and breast cancer and its metastasis risk, it seems that both DPP-4 inhibitors and GLP-1 receptor agonists can be considered neutral, or even beneficial (decreased risk of colorectal cancer in case of DPP-4 inhibitors)." (PMID 33562380, 2021). "The accumulation of DPP4 could protect cells from ferroptosis by inhibiting lipid peroxidation in human colorectal cancer." (PMID 34277151, 2021). "In contrast, DPP-4 inhibitor users had no elevated risk of colorectal cancer incidence in diabetic patients, and that the DPP-4 inhibitor was also associated with a significantly reduced risk of colorectal cancer among T2DM patients." (PMID 34063285, 2021). "To further clarify the role of DPP4i, we conducted a SEER (Surveillance Epidemiology and Endpoint Research)-Medicare analysis of colorectal cancer and lung cancer patients, which also showed a similar trend toward beneficial effects associated with CD26/DPP4 inhibition." (PMID 32296640, 2020).
colorectal cancer (continued). "DPP4 is upregulated in many aggressive types of T-cell malignancies, esophageal adenocarcinoma, lung adenocarcinoma, thyroid carcinoma, and prostate cancer, and a high level of DPP4 is indicative of poor prognosis for papillary thyroid carcinoma, urothelial carcinoma, and colorectal cancer." (PMID 32294701, 2020). "Functional analysis revealed upregulation of microbial proteins related to DPP-4 and cysteine metabolism, suggesting a possible role of microbiome-derived enzymes in colorectal cancer-associated metabolic and immune modulation, without direct evidence of host translocation." (PMID 41742010, 2026). "Specifically, we tested whether DPP4 reconstitution enhances sensitivity to ICIs in the MC38 colorectal cancer cell line, which does not harbor KRAS mutations." (PMID 41283988, 2025). "We have previously shown that the dietary flavone apigenin (4′,5,7-trihydroxyflavone) upregulates cell-surface CD26/DPP4 on human colorectal carcinoma (CRC) cells and regulates its activities." (PMID 36618939, 2022). "Second, the potential involvement of other DPP family members, particularly DPP4, which has been implicated in cancer progression and immune regulation, should be explored to determine whether they function redundantly or distinctly from DPP7 in colorectal cancer." (PMID 40576169, 2025). "DPP4 (CD26) inhibition elevates CXCR3 ligands, enhances CXCR3+ NK/T cell infiltration, and improves responses in melanoma, glioblastoma, and colorectal cancers." (PMID 40361472, 2025). "Despite the first study on colorectal cancer (CRC) reporting reduced levels of enzymatic activity in a small group of patients, other studies found increased DPP4 activity." (PMID 39001488, 2024). "Although we focus on T-cell malignancies in the following, it should be mentioned that several solid tumors including for example colorectal cancer (CRC), hepatocellular cancer (HCC), malignant mesothelioma and renal cell carcinoma (RCC) express CD26/DPP4." (PMID 34885056, 2021). "DPP4 inhibition has been reported to improve progression-free survival (PFS) in advanced airway and colorectal cancer patients with T2DM." (PMID 34955820, 2021). "In syngeneic models of melanoma and colorectal cancer (B16F10 and CT26 models, respectively), inhibition of DPP4 by sitagliptin or DPP4 knockout led to enhanced T cell infiltration, impaired tumor growth and less metastatic spread." (PMID 31482487, 2019).
colorectal cancer (continued). "We studied whether the blood biomarker soluble-CD26 (sCD26), a glycoprotein with dipeptidyl peptidase enzyme activity (DPP4), could help in the early diagnosis of colorectal cancer and advanced adenomas in combination with FIT, and/or reducing false positives." (PMID 36230486, 2022). "We studied whether the blood biomarker soluble-CD26 (sCD26), a glycoprotein with dipeptidyl peptidase enzyme activity (DPP4), could help in the early diagnosis of colorectal cancer and advanced adenomas in combination with FIT, also reducing false positives." (PMID 36230486, 2022). "Interestingly, the expression of DPP4/CD26 defines a cancer cell subpopulation displaying CSC-like features and correlated with poor prognosis in human colorectal cancer, suggesting that this population could be effectively targeted by ferroptosis inducers." (PMID 34831207, 2021).
Hypertension (89 papers, 2011 to 2025). The presence of chronic increased pressure in the systemic arterial system. "There have been several clinical studies of the potential effects of DPP-4 inhibitors on CV risk factors including hypertension." (PMID 23710467, 2013). "The vascular activity and expression of DPP4 are increased in hypertensive rats, suggesting that this peptidase may contribute to impaired vascular function associated with high blood pressure." (PMID 33329052, 2020). "Circulating DPP4 levels predict the development of type two diabetes, atherosclerosis and hypertension." (PMID 40514620, 2025). "Current research indicates that DPP-4 inhibitors can help with hyperlipidemia, hypertension, calcified aortic valve disease, and coronary atherosclerosis; however, their potential benefit for HF is still up for debate." (PMID 40429343, 2025). "Sixth, the HR and 95% CI of developing hypertension in SGLT2i users was 0.93 (0.86–1.01) compared to that in DPP4 inhibitor users after excluding individuals who had any antidiabetic medications at the index date." (PMID 38600275, 2024). "Uric acid and incretin or dipeptidyl peptidase 4 activity alteration also contribute to the development of hypertension in the context of obesity." (PMID 34845309, 2021). "Dipeptidyl peptidase-4 inhibitors (DPPIV) or neprilysin (neutral endopeptidase) inhibitors used in the treatment of hypertension can increase the propensity of drug-induced angioedema significantly when combined with ACEi." (PMID 33534062, 2021). "A number of studies have indicated the protective effects of DPP-4 inhibitors in cardiovascular diseases including hypertension." (PMID 34368236, 2021). "To verify the anti-hypertensive effect of DPP-4 inhibitor MK-626 in hypertension, we first measured the systolic blood pressure (sBP) before and after 2 weeks Ang II infusion with or without MK-626 treatment." (PMID 34368236, 2021). "DPP4 inhibition has also mitigated LV remodeling and dysfunction in other experimental models of hypertension, such as spontaneously hypertensive rats and Dahl salt-sensitive rats." (PMID 33329052, 2020). "Accordingly, extensive studies have shown that DPP4 inhibitors play a protective effect against hypertension-related vascular events, such as endothelial dysfunction and increased arterial stiffness." (PMID 33329052, 2020). "The antihypertrophic effects of the DPP4 inhibitor teneligliptin have been recently unraveled in an experimental model of Ang II-induced hypertension." (PMID 33329052, 2020). "There were significant differences in mean age and the proportions of patients with a medical history of ischemic heart disease and hypertension, and treatment with antidiabetic drugs and lipid-lowering drugs among the five groups of DPP-4 inhibitor users." (PMID 32317005, 2020). "Some studies suggest that GLP-1 analogues or DPP-4 inhibitors improve endothelial functioning by promoting activation of eNOS and enhancing NO production to prevent the progression of hypertension or atherosclerosis." (PMID 31772770, 2019). "In a pre-clinical study, pharmacological inhibition of DPP4 that reduced plasma DPP4a results in improved hypertension rates." (PMID 28587613, 2017). "The logistic regression analysis revealed that CAD significantly associated with age, gender, hs-CRP, hypertension, LDL-C, and DPP4." (PMID 27654253, 2016). "Some clinical data suggest the beneficial effects of DPP-4 inhibitors on hypertension, dyslipidemia and CRP have been cited in the literature." (PMID 27006706, 2016). "DPP-4 inhibition improves age-related diseases, such as hypertension, dyslipidemia, hepatic steatosis, and neurodegenerative diseases." (PMID 26937254, 2016). "Thus, the antihypertensive effect via the ACE inhibitory activity of a DPP4 inhibitory peptide is expected to be beneficial for the management of T2D patients with hypertension, as well as for hypertension patients with T2D." (PMID 39595018, 2024).